PAX3 (paired box 3)
Diseases named in the same sentence as PAX3 in open-access papers (continued):
Sharing a sentence is not in itself a finding about the gene and the disease.
glioma (12 papers, 2014 to 2025). A benign or malignant brain and spinal cord tumor that arises from glial cells (astrocytes, oligodendrocytes, ependymal cells). "In our study, elevated PAX3 expression in glioma was associated with enhanced cell proliferation, migration, and reduced sensitivity to the histone deacetylase inhibitor vorinostat." (PMID 41180518, 2025). "Further exploration into its molecular associations unveils intriguing links between PAX3 expression and various oncogenes, suggesting its potential role as an oncogenic driver in glioma progression." (PMID 41180518, 2025). "In the realm of glioma research, PAX3 stands out among the ERGs identified in our risk model, boasting the strongest correlation with the risk score." (PMID 41180518, 2025). "PAX3 is overexpressed in glioblastomas and it contributes to features of glioma stem cells, which has been identified as a diagnostic/prognostic marker and a therapeutic target." (PMID 37955724, 2023). "Functionally, Pax3 has been implicated in promoting proliferation and invasion and inhibiting apoptosis of glioma cell lines, and promoting growth of glioma subcutaneous xenografts." (PMID 25330836, 2014). "PAX3, which has been implicated in glioma tumorigenesis is co-expressed with ZIC1." (PMID 34475426, 2021). "PAX3 was upregulated in glioma cells, and was associated with a poorer prognosis for patients." (PMID 33503296, 2021). "Importantly, addition of Pax3 to PDGF-B overexpression caused a subset of tumors to progress to high-grade glioma based on the presence of microvascular proliferation (0/5 PDGF-B versus 5/20 PDGF-B + Pax3 high-grade, p = 0.056)." (PMID 25330836, 2014). "To investigate PAX3's role in glioma cell dynamics, we manipulated its expression using shRNA and overexpression plasmids." (PMID 41180518, 2025). "This study aimed to construct and validate a prognostic model for glioma based on epilepsy-related genes (ERGs) and to investigate the functional role of PAX3 in glioma progression and drug response." (PMID 41180518, 2025). "Analysis across multiple datasets, including TCGA-LGGGBM, GSE4290, and GSE50161, has consistently revealed heightened expression of PAX3 in glioma tissues compared to their normal counterparts." (PMID 41180518, 2025). "The results demonstrated that PAX3 knockdown markedly reduced glioma cell migration, whereas overexpression enhanced it." (PMID 41180518, 2025). "Functional experiments demonstrated that PAX3 promotes glioma cell proliferation and migration, accompanied by modulation of epithelial–mesenchymal transition (EMT) markers." (PMID 41180518, 2025). "In conclusion, this study developed and validated a four-gene ERG-based prognostic model with high clinical utility and identified PAX3 as a potential therapeutic target that drives glioma cell migration and vorinostat sensitivity." (PMID 41180518, 2025). "Consistent findings were observed in the EdU assay, where PAX3 knockdown attenuated glioma cell proliferation, whereas its overexpression augmented this process." (PMID 41180518, 2025). "The results from the CCK-8 assay unveiled a significant inhibition of cell proliferation of U251 and U87 cells upon PAX3 knockdown, while overexpression of PAX3 notably promoted glioma cell proliferation." (PMID 41180518, 2025).
glioma (continued). "Despite these limitations, our study presents a validated four-gene ERG-based model and highlights PAX3 as a potential therapeutic target, providing a foundation for more personalized glioma therapy." (PMID 41180518, 2025). "In glioma specimens, 97.6% showed a positive PAX3 expression, while it was only 16% in normal brain tissues." (PMID 29937714, 2018). "In order to determine if Pax3-induced inhibition of apoptosis is sufficient to induce glioma in vivo, P3 Ntv-a mice were injected in the brainstem with RCAS-Pax3, RCAS-PDGF-B, or a 1:1 mixture of both viruses." (PMID 25330836, 2014). "As Nestin cells are the targeted cell-of-origin for the BSG model used here, it is possible that Nestin+/Pax3+ progenitors give rise to Pax3-High glioma in this mouse model." (PMID 25330836, 2014). "High Pax3 expression characterizes PDGF-B-driven mouse BSG while its expression is lower in glioma arising in the cerebral cortex." (PMID 25330836, 2014). "In the neonatal mouse brain, Pax3 expression marks a subset of brainstem progenitor cells, while it is absent from the cerebral cortex, mirroring its regional expression in glioma." (PMID 25330836, 2014). "In summary, the data presented here show that mouse BSG and a subset of human BSG highly express Pax3, distinguishing these tumors from gliomas arising in the cerebral cortex." (PMID 25330836, 2014). "Pax3 is re-expressed and upregulated in human glioma relative to normal brain tissue with its expression increasing concomitant with World Health Organization Grade and worsening prognosis, irrespective of tumor location." (PMID 25330836, 2014). "Further investigation into the expression of Pax3 along with other glioma markers in the developing mouse and human brainstem will be the focus of future studies to hopefully clarify this issue." (PMID 25330836, 2014). "Based on our direct comparison between BSG and CG, we would expect the levels of Pax3 expression in these supratentorial gliomas to be lower than in BSG." (PMID 25330836, 2014). "The Pax3-induced high-grade gliomas harbored increased proliferation compared to the low-grade tumors induced by PDGF-B alone based on PCNA staining." (PMID 25330836, 2014). "One gene found to be expressed at higher levels in infratentorial compared to supratentorial low-grade glioma is paired box 3 (PAX3)." (PMID 25330836, 2014). "The pro-tumorigenic role of Pax3 in glioma is brainstem-specific, as co-injection into the cortex of both PDGF-B and Pax3 did not significantly reduce survival or increase tumor penetrance (p = 1.0) or grade (p = 1.0) compared to injection of PDGF-B alone." (PMID 25330836, 2014). "Intriguingly, CCK-8 assays revealed that PAX3 knockdown increased the sensitivity of U251 and U87 cells to vorinostat, highlighting a potential role of PAX3 in modulating drug sensitivity in glioma cells." (PMID 41180518, 2025). "PAX3 emerged as a key regulator of glioma migration and vorinostat response, yet its function may vary across molecular subtypes such as mesenchymal and proneural." (PMID 41180518, 2025). "Similarly, wound scratch healing assays revealed a decelerated wound closure rate in glioma cells upon PAX3 knockdown." (PMID 41180518, 2025). "GSEA enrichment analysis provides further insights into the functional relevance of PAX3 in glioma biology, linking it to key cancer-related biological processes and KEGG pathways such as neurotransmitter secretion, immune response to tumor cells, and cell cycle regulation." (PMID 41180518, 2025). "Furthermore, we examined the expression of PAX3 in the established human glioma cell lines (U87 MG, U251 MG) and the normal astroglial cell line, 1800." (PMID 29937714, 2018).
glioma (continued). "We next investigated whether Pax3 expression characterizes any Nestin-progenitors, the targeted cell-of-origin in our glioma mouse model, in the P3 mouse brainstem." (PMID 25330836, 2014). "The regional expression pattern of Pax3 in glioma correlates with its expression in the developing mouse brain, pointing to the possibility that the expression level of Pax3 in different regions of the developing brain dictate its expression level in gliomas arising in those regions." (PMID 25330836, 2014). "Importantly, the regional expression pattern of Pax3 is mirrored in human glioma, revealing a subset of BSG with high PAX3 expression that associates with alterations in PDGFRA and cell cycle regulatory genes and is exclusive of ACVR1 mutations." (PMID 25330836, 2014). "Thus the regional expression pattern of Pax3, and its co-expression with Nestin, in the neonatal mouse brain correlates with its expression in glioma." (PMID 25330836, 2014). "This expression pattern of Pax3 is mirrored in the developing brain, which may account for the gene’s regional specificity in glioma." (PMID 25330836, 2014). "Moreover, PAX3 could facilitate cell proliferation and invasion, inhibit apoptosis, and played an oncogenic role in gliomas through promoting proliferation." (PMID 33503296, 2021). "Importantly, Pax3 is regionally expressed in human glioma as well, with high PAX3 mRNA characterizing 40% of human BSG, revealing a subset of tumors that significantly associates with PDGFRA alterations, amplifications of cell cycle regulatory genes, and is exclusive of ACVR1 mutations." (PMID 25330836, 2014). "Mechanistically, PAX3 expression positively correlated with HDAC1/2/3 levels, and its knockdown increased glioma cell sensitivity to vorinostat." (PMID 41180518, 2025). "Experimental data using a glioma cell line which does not express miR-1 but expresses high levels of Pax3 showed that transfecting cells with miR-1 led to reduced levels of both Pax3 transcript and protein at 48 h13." (PMID 28951568, 2017). "While PDGF-B overexpression alone led to asymptomatic low-grade glioma in 5 out of 20 mice, Pax3 overexpression alone did not lead to tumor formation." (PMID 25330836, 2014). "Moreover, PAX3 expression demonstrates significant positive correlations with multiple immune checkpoints, particularly PDCD1, SIGLEC7, and LILRB2, underscoring its involvement in immune regulation within the glioma microenvironment." (PMID 41180518, 2025). "By Western blot, PAX3 protein was detected in wildtype P3 brainstem but not cerebral cortex (cerebellum is shown as a positive control), consistent with its expression pattern in glioma." (PMID 25330836, 2014).
Hyperglycemia (12 papers, 2016 to 2025). An increased concentration of glucose in the blood. "Hyperglycaemia during embryogenesis induces hypoxia, leading to reduced PAX3 expression, which can cause CDH." (PMID 38398855, 2024). "This suggests that oxidative stress induced by maternal hyperglycemia phenocopies the effect of Pax3 loss-of-function mutation." (PMID 34439421, 2021). "RT-qPCR revealed that the expression of Myf5 and Pax3, which are markers of myoblasts, were upregulated by intrauterine hyperglycaemia." (PMID 39043630, 2024). "Experimental studies found that hyperglycaemia in early pregnancy affected regulatory gene expression in the embryo for genes, such as Bmp4, Msx1, and Pax3, leading to cardiac neural crest cell death and an increased risk of CHD." (PMID 33062711, 2020). "Recently, evidence from animal studies suggested that aberrant methylation of Pax3 was involved in the development of NTDs induced by hyperglycemia." (PMID 30665459, 2019). "In the present study, a negative correlation between gene body DNA methylation and transcription level of Pax3 was observed in mouse embryos, which was in line with the finding in hyperglycemia-induced NTDs." (PMID 30665459, 2019). "5f restored the expression of paired box type 3 transcription factor (Pax3), and reduced the hyperglycemia-induced increase of ALR2 activity, sorbitol accumulation, and the generation of ROS and MDA to normal levels." (PMID 27109517, 2016). "Raising O-GlcNAc levels by injecting glucose or the highly specific OGA inhibitor Thiamet G (TMG) into chicken egg embryos decreased PAX3 protein expression, while hyperglycemia did not affect PAX3 mRNA levels." (PMID 29790000, 2018).
hearing loss (11 papers, 2014 to 2025). "Normothermia TTM upregulated 13 genes associated with hearing loss, including Loxhd1, Tecta, Zmiz1, Espn, Gjb2, Sesn3, Bdp1, Hg, Pax3, Rnls, Syne4, P2rx2, and Pou3f4." (PMID 38298897, 2023). "Among the WS patients who participated in this study, all patients with SOX10 mutations have hearing loss, while some patients with PAX3 (3/7) or MITF (2/3) have." (PMID 34149797, 2021). "In F10, the phenotype of hearing loss in III-1 was overshadowed by the presence of clinical findings of PAX3-related WS." (PMID 34276053, 2021). "Mutations of PAX3 have been proven to be associated with hearing loss." (PMID 36118891, 2022). "However, we constructed the family pedigree based on the hearing-impaired phenotype, which suggested that the de novo mutation (c.91-95delACTCC) identified in PAX3 was the likely cause of genetic transmission of hearing loss in the patient’s family." (PMID 30314436, 2018). "A mutated paired box 3 (PAX3​​​​​) gene manifests as type 1 Waardenburg, which is characterized by sideways displacement of the inner angles of the eyes (i.e., dystopia canthorum), widely spaced eyes, congenital sensorineural hearing impairment, and patchy pigmentation of the iris, skin, and hair." (PMID 38854277, 2024).
breast carcinoma (10 papers, 2015 to 2026). "Interestingly, LY6K expression was lower in the SNP242 mutation which creates de novo PAX3 transcription factor binding sites in breast cancer cell lines." (PMID 27494879, 2016). "The central genes of the network (RUNX1, PAX3, GATA4 and DLX5) were subjected for epigenetically dysregulation in association with different breast cancer subtypes." (PMID 28747748, 2017). "The central genes of the network were identified and RUNX1, PAX3, GATA4 and DLX5 genes were subjected for epigenetically dysregulation in association with diversity of breast cancer subtypes." (PMID 28747748, 2017). "While an increase of KDM3A is concomitant with a reduced H3K9me2/3 during breast tumorigenesis, KDM3A facilitated the activation of genes implicated in breast cancer as MYC, PAX3, Cyclin D1, MMP-9, S100A4, and JUN, thereby enhancing the proliferation and motility of breast cancer cells." (PMID 36185256, 2022). "Intriguingly, comparative analysis with other PAX family members (e.g., PAX3 and PAX9) revealed that PAX7 exhibits unique oncogenic specificity in breast cancer." (PMID 41532150, 2026). "The results suggested KDM3A/JMJD1A regulates the tumorigenesis of breast cancer through down-regulating H3K9me2 on oncogenes MYC and PAX3." (PMID 27034728, 2016). "However, no significant change of cell viability was found after Pax3 overexpression in the LLC lung cancer cell line, the 4T1 murine breast cancer cell line and the MC38 colon cancer cell line." (PMID 33336498, 2021).
synovial sarcoma (10 papers, 2011 to 2025). "Cre/LoxP-driven mouse synovial sarcoma (SS) most readily forms in a Myf5-expressing skeletal muscle-specific lineage, whereas fusion oncogene expression in early myogenic precursors (Pax3/Pax7) was fatal and myofiber expression (Myf6) caused myopathy." (PMID 38916046, 2024).
deafness (9 papers, 2016 to 2025). An inherited or acquired condition characterized by the complete loss of the ability to hear from one or both ears. "Among DBE cats carrying a non-coding PAX3 variant, bilateral deafness was observed in homozygous DBEALT/DBEALT cats or in compound heterozygous DBECEL/DBEALT cats." (PMID 38997957, 2024). "There are no major differences between Splashed White phenotypes caused by mutations in MITF and PAX3, and mutant alleles for either gene are tied to an increased risk of deafness." (PMID 38338094, 2024). "Moreover, in adherence to the German Animal Protection Law, the breeding of animals with defective organ systems is explicitly prohibited, a criterion met by the PAX3-associated deafness described in this study." (PMID 38869246, 2024). "Among Maine Coon cats carrying the PAX3:c.937C>T nonsense variant (DBERE allele), unilateral and bilateral deafness has been confirmed using the BAER test in heterozygous cats." (PMID 38997957, 2024). "Three of the ten Splashed White alleles are attributed to mutations in PAX3 on ECA6 and cause depigmentation of the hair, skin, and eyes as well as an increased risk for deafness." (PMID 38338094, 2024). "Genotype association of the PAX3 and KIT variants with DBE, deafness, and white spotting in 299 cats (for coat color patterns of the studied cats)." (PMID 38869246, 2024). "Together with the comparative data from other species, our findings strongly suggest PAX3:c.937C>T (OMIA:001688-9685) as the most likely candidate variant for the DBE, deafness, and minimal white spotting in the Maine Coon Dutch line." (PMID 38869246, 2024). "Phenotypes caused by the genes endothelin 3 (END3), endothelin receptor B (EDNRB), microphthalmia-associated transcription factor (MITF), paired box 3(PAX3), SRY-box 10 (SOX10), and snail homolog 2 (SNAI2) can result in decreased melanocytes, white coat color, and ultimately deafness." (PMID 27698666, 2016). "While non-coding variants do not lead to deafness in heterozygous individuals, the cumulative impact of two mutant alleles in homozygous animals may compromise PAX3 function." (PMID 38997957, 2024). "Thus, in feline PAX3-related DBE, deafness appears to depend on the molecular defect." (PMID 38997957, 2024).